TNF (tumor necrosis factor)
Diseases named in the same sentence as TNF in open-access papers (continued):
Sharing a sentence is not in itself a finding about the gene and the disease.
Insulin resistance (continued). "The pro-inflammatory cytokine TNF-α is associated with insulin resistance, and an HFD of both lard and soybean oil can increase TNF-α expression levels in adipose tissue." (PMID 36839280, 2023). "On the one hand, it has been reported that insulin resistance causes the overproduction of free fatty acids, releasing pro-inflammatory cytokines such as tumor necrosis factor-α (TNF-α) and nuclear factor-κB (NF-κB) into the blood circulation." (PMID 37238649, 2023). "Diet quality also influenced circulating adiponectin levels and TNF-α, associated with low-grade inflammation, possibly leading to insulin resistance and diabetes and contributes to the pathogenesis of atherosclerosis." (PMID 38188871, 2023). "Taking these findings together, insulin resistance is associated with both T-cell senescence and TNF-α production by senescent CD8 + T cells, and correlates with the degree of hepatic fibrosis in patients with T2D." (PMID 37735474, 2023). "Insulin resistance and glucose intolerance are inflammatory syndromes linked to TNF-α, interleukin-1, and decreased adiponectin production." (PMID 36653874, 2023). "Single nucleotide variations in the TNF-α gene have also been implicated in increased insulin resistance typical of type 2 diabetes." (PMID 37215099, 2023). "Tumor necrosis factor (TNF)-α was the first proinflammatory cytokine to be implicated in the pathogenesis of insulin resistance and type 2 diabetes." (PMID 37215099, 2023). "The increase in TNF-α observed in the adipose tissue of obese patients is directly associated with the insulin resistance in obese patients." (PMID 37990213, 2023). "In T2DM, one of the markers also involved in AD is inflammation that is caused due to insulin resistance in diabetes, which in turn causes a surge in proinflammatory cytokines (IL-6, IL-1 beta) and tumor necrosis factor-alpha (TNF-α)." (PMID 38067154, 2023). "The amount of inflammatory markers (IL-6, TNF-α, and LPS) in T2D is increased, which is associated with dysfunction in insulin resistance and β-cell activity, and the amount of LPS in diabetic patients is twice as high as that in healthy individuals." (PMID 36900540, 2023). "Higher plasma concentrations of TNF-alpha have been implicated in the development of insulin resistance." (PMID 37139450, 2023). "The recruitment of macrophages is the main characteristic of inflammation in white adipose tissue and promoted the secretion of TNF-α, IL-2, and IL-6 which cause insulin resistance." (PMID 36647430, 2023). "HIF-2α+/– mice indeed display ATM accumulation, insulin resistance and susceptibility to adipose tissue inflammation (TNFα and IL-6) upon overnutrition." (PMID 34876704, 2022). "A large amount of IL-6 in a high-glucose environment can reduce insulin sensitivity, and excessive TNF-α will cause an increase in the free fatty acid content, which will eventually lead to insulin resistance." (PMID 35327635, 2022). "It has been proven that adipose tissue-resident macrophages lead to the release of TNF-α and IL-6, which are implicated in the induction of insulin resistance." (PMID 36353235, 2022). "In humans, the circulating concentration of TNF-α is elevated in T2D, and this alteration is associated with impaired glucose tolerance and enhanced insulin resistance, in addition to an increased risk of T2D." (PMID 36552772, 2022). "Pro-inflammatory cytokines, such as TNF-α and IL-6, disrupt the insulin signaling pathway, and cause insulin resistance." (PMID 35745208, 2022). "Increased fat levels cause inflammatory cytokines, such as tumor necrosis factor-alpha and interleukin (IL)-634, to be secreted, as well as insulin resistance, which contribute to MetS." (PMID 35162353, 2022). "High levels of proinflammatory cytokines such as IL-6 and TNF-α in diabetes cause disruption of the inflammatory cascade, hyper inflammation, and insulin resistance." (PMID 35186344, 2022).
Insulin resistance (continued). "They found that adipose tissue from different obese rodents and humans has an enhanced secretion of proinflammatory cytokines, mainly TNF, which was linked to insulin resistance." (PMID 36119080, 2022). "Studies have shown that inflammation is associated with insulin resistance, and the most vital pro-inflammatory mediators include tumor necrosis factor-α (TNF-α) and interleukin 6 (IL-6)." (PMID 36232291, 2022). "As a result, increased TNF-α synthesis and secretion in the context of inflammation have been linked to the development of insulin resistance and the pathogenesis of metabolic disorders." (PMID 35406450, 2022). "Macrophages produce cytokines such as IL-6 and tumor necrosis factor alpha (TNFα), which also play a role in causing insulin resistance." (PMID 35216172, 2022). "TNFα has long been implicated in development of insulin resistance, and reduced TNFα activity improves systemic insulin resistance." (PMID 36200038, 2022). "The activation promotes the expression of target genes IL-6 and TNF-α to cause low-grade systemic inflammation and insulin resistance." (PMID 36235858, 2022). "Subsequent studies reported that TNF-α-deficient mice were free from high-fat diet-induced insulin resistance." (PMID 35563728, 2022). "In parallel, in mice fed a normal chow diet, administration of P. gingivalis also induces insulin resistance associated with decreased Akt phosphorylation and increased TNF-α expression in the soleus muscle." (PMID 35327570, 2022). "During pregnancy, TNF-α secreted by the placenta causes inflammatory cell aggregation and impairs insulin resistance." (PMID 36263320, 2022). "Insulin resistance caused by obesity is related to the development of a chronic low-grade inflammatory state and the action of adipokines, such as leptin, resistin, TNF-α, IL-6, MCP-1, and CRP." (PMID 36262532, 2022). "TNF-α expression in adipose tissue has been linked to insulin resistance, which is considered a key pathogenic mechanism in the development of T2D." (PMID 35627115, 2022). "These inflammatory markers, such as tumor necrosis factor alpha (TNF-a), interleukin 6 (IL-6), C-reactive protein, and leptin, influence insulin resistance and growth hormone and cause an imbalance in protein synthesis, and lead to poor physical capacity." (PMID 35875029, 2022). "One study showed that mRNA expression levels of TNF-α in adipose tissue in obese individuals are strongly implicated in the pathogenesis of insulin resistance through impairment of insulin signaling in hepatocytes and adipose tissue." (PMID 35457158, 2022). "TNF-α can activate IL-6, IL-8, and other cytokines, form an inflammatory cascade, induce liver inflammation, lead to insulin resistance (IR), and cause NASH." (PMID 36091584, 2022). "We have not elucidated the precise mechanism by interactions between TNF-α and the loss of insulin receptor and subsequent insulin resistance." (PMID 35198097, 2022). "An increase in TNF-α was associated with insulin resistance, increased plasma glucose, and insulin prior to the onset of T2DM." (PMID 36140983, 2022). "TNF-α can also cause insulin resistance by damaging pancreatic P cells, thereby increasing serum uric acid levels." (PMID 35216583, 2022). "TNF-α causes insulin resistance in animals by itself or by increasing circulating levels of free fatty acids." (PMID 35959169, 2022). "For example, in patients with rheumatoid arthritis and diabetes, anti-TNFα inhibitor therapy attenuated the patients’ insulin resistance and improved insulin sensitivity, also the risk for developing Alzheimer’s disease was reduced." (PMID 35328666, 2022). "Further, the VAI was associated with chronic inflammation and insulin resistance, due to increases in free fatty acids, interleukin-6, tumor necrosis factor-α, and decreased adiponectin production, related to VAT." (PMID 35811709, 2022).
Insulin resistance (continued). "Several research investigating the relationship between TNF polymorphism with insulin resistance and T2D risk have been published in various countries." (PMID 35627115, 2022). "Previous research has shown that excessive production of pro-inflammatory cytokines (TNF-α, IL-1β, IL-6) causes chronic inflammation and insulin resistance." (PMID 36056976, 2022). "We presumed that IL-6 and TNF-α were associated with a pro-inflammatory state leading to insulin resistance and diabetes." (PMID 36140983, 2022). "High levels of proinflammatory cytokines in diabetes, such as IL-6 and TNF-α, cause disruption of the inflammatory, hyperinflammatory cascade, and insulin resistance." (PMID 35186344, 2022). "TNF-α has been found to induce hepatic inflammation and subsequent apoptosis associated with insulin resistance." (PMID 35806336, 2022). "Because of cytokine release, especially TNFα, a high number of classically activated M1 macrophages infiltrate the adipose tissue, which is associated with insulin resistance." (PMID 35422689, 2022). "Two commonly measured cytokines, IL-6 and TNF-α, have been associated with insulin resistance, diabetes, and obesity, cardiac disease, and cancer in humans." (PMID 36230446, 2022). "Overproduction of pro-inflammatory cytokines such as tumor necrosis factor alpha (TNFα) and interleukin (IL)-1β is associated with insulin resistance." (PMID 34816303, 2022). "As increased TNF-α and IL-6 are associated with the pathogenesis of insulin resistance, biologic DMARDs (e.g., TNF inhibitors and tocilizumab) were expected to decrease DM risk by increasing insulin sensitivity." (PMID 35456202, 2022). "Increased levels of proinflammatory cytokines such as TNF-α IL-1, and IL-6 have been shown to promote insulin resistance and cause metabolic disturbances in children with vitiligo." (PMID 37632859, 2022). "Relevant in this context is the role of both TNF-α and IL-6 that induce an altered expression of insulin receptors with consequent worsening of insulin resistance status and associated hyperglycemia." (PMID 36142799, 2022). "TNF-α is mostly expressed in adipose cells and is associated with insulin resistance, while highly expressed IL-6 causes cytotoxicity in pancreatic β cells." (PMID 36276816, 2022). "Insulin resistance is also caused by TNF-α in peripheral tissues, such as the liver, muscle, and adipocytes." (PMID 35055191, 2022). "Since vitamin B12 deficiency is associated with abnormal TNF-α activity, it can also lead to insulin resistance." (PMID 36570149, 2022). "Interleukin-1 (IL-1), interleukin-6 (IL-6), and tumor necrosis factor-α (TNF-α) are inflammatory cytokines that cause insulin resistance and also suppress insulin release, an effect that is concentration-dependent." (PMID 35959169, 2022). "Tumor necrosis factor-α (TNF-α) is a cytokine that has been found to play a role in insulin resistance and the TNF-α gene is one of the candidate genes implicated in type 2 diabetes mellitus (T2DM)." (PMID 35052401, 2021). "Inflammatory cytokines such as TNF-α are critical factors causing insulin resistance of tissues 33-35." (PMID 33746602, 2021). "Our results showed LE increased PPARγ, GLUT4 and DGAT-1 levels, demonstrating the potential of this lemon extract in the management of insulin resistance conditions associated with TNF-α pathway activation." (PMID 34361563, 2021). "The most important of these is TNF-α, which has been associated with the development of insulin resistance and increased lipase activity." (PMID 35050141, 2021). "The presence of proinflammatory cytokines, such as IL-6, IL-1, and TNF-α, has been linked to the pathogenesis of insulin resistance and endothelial dysfunction in metabolic syndrome, contributing to the presence of diffuse subclinical inflammation." (PMID 34445526, 2021). "Tumor necrosis factor α and leptin have also been implicated as contributors to insulin resistance and hyperglycemia in pregnancy." (PMID 34126994, 2021).
Insulin resistance (continued). "Low-grade chronic inflammation, with excess fat driving the release of proinflammatory cytokines such as TNF and IL-1β 46, is associated with adiposity, insulin resistance, hyperleptinemia, metabolic syndrome and type 2 diabetes 47–51." (PMID 33658532, 2021). "IL-6 is responsible for insulin resistance and has been associated with hypertension and atherosclerosis in murine models while TNF-α is a mediator of atherosclerosis and heart failure." (PMID 34445526, 2021). "The recruitment of macrophages in adipose tissue is associated with increased IL-6 and TNF-α secretion, leading to insulin resistance." (PMID 34356649, 2021). "Tumor necrosis factor alpha (TNF-α), a cytokine produced in the placenta and adipose tissue, is elevated in late pregnancy and associated with insulin resistance." (PMID 33467738, 2021). "The mechanisms underlying insulin resistance are, however, very complex, and the activation of TNFα signaling pathway has extensive ramifications on the intercellular environment that remain largely unexplored." (PMID 34576943, 2021). "High levels of TNFα have been linked to the development of insulin resistance in several tissues and organs, including skeletal muscle and the liver." (PMID 34576943, 2021). "TNFR1 in the TNF signaling pathway mainly regulates cell regulation processes and is associated with insulin resistance and the pathogenesis of type 2 diabetes.The study showed that TNF-α levels increased significantly at the generation of oxidative stress." (PMID 34692849, 2021). "PCOS is a chronic inflammatory condition associated with increased serum TNFα and decreased serum adiponectin concentrations, which accompany insulin resistance and dyslipidemia." (PMID 34805198, 2021). "Impaired glucose metabolism and insulin resistance are associated with low-grade chronic inflammation, and TNF-α and IL-6 are proposed targets, inter-linking inflammation and insulin resistance." (PMID 34073455, 2021). "TNF-α, which is primarily secreted by adipose tissue-resident macrophages, was the first inflammatory cytokine to be implicated in the induction of insulin resistance." (PMID 33800490, 2021). "Anti-TNFα agents improve insulin sensitivity and decrease insulin resistance in RA patients, also reducing the risk of developing T2D." (PMID 33995414, 2021). "This indirectly prevents adipocyte hypertrophy and tissue inflammation and attenuates the effect of cytokines implicated in insulin resistance (e.g., TNFα and MIF signaling), as observed herein." (PMID 34444996, 2021). "Although the possible role of miRNA-122 in modulation of inflammatory cascades is well described, the exact mechanism through which miRNA-122 affects TNF-α and IL-6 levels consequently linked to insulin resistance in T2DM patients remains poorly understood." (PMID 34077450, 2021). "Nutrient excess and high-fat diets are known to recruit neutrophils into tissues, which then cause insulin resistance both by releasing TNF-⍺ and IL-6 and by upregulating cyclooxygenase." (PMID 34099068, 2021). "The expression of TNF-α, an inflammatory cytokine associated with chronic inflammation and insulin resistance (IR), decreased in the three seaweed groups as compared to the LPS stimulated group." (PMID 33540936, 2021). "Two main adipose tissue-derived inflammatory cytokines have been implicated in insulin resistance including TNF-α and IL-6." (PMID 33800490, 2021). "Based on these results, we conclude that DHM improved insulin resistance caused by TNF‐α, promoted protein synthesis in C2C12 cells and finally exerted DHM function of resisting inflammation‐induced muscle atrophy." (PMID 34676967, 2021). "TNF signaling pathway: there was a growing evidence that tumor necrosis factor-α (TNF-α) involved in insulin resistance, and it is associated with the development of T2DM." (PMID 34349832, 2021).
Insulin resistance (continued). "Correspondently, in adipocyte cultures, TNF-α-mediated insulin resistance is associates with increased ROS production and JNK activation." (PMID 34680177, 2021). "Pro-inflammatory adipokines, such as interleukin-6, tumor necrosis factor α (TNFα), serpin family E member 1, and monocyte chemoattractant protein-1, cause inflammatory reactions and insulin resistance." (PMID 34199596, 2021). "TNF-α plays a critical role in mediating insulin resistance associated with high-fat diet and targeting TNF-α increases insulin sensitivity." (PMID 35082682, 2021). "It is possible that IL-6 in combination with other inflammatory markers such as IL-1b, TNF-a, IL-18 and IL-17 links insulin resistance to NMOSD risk." (PMID 33879088, 2021). "A high concentration of TNF-α is associated with insulin resistance, but transmembrane TNF-α has been found to be involved in defense against infection and cancer." (PMID 34239993, 2021). "High BMI and increased adipose tissue are positively associated with inflammatory markers such as TNF-α, insulin resistance, and β-cell dysfunction." (PMID 34215245, 2021). "TNF-alpha concentration is also linked with peripheral insulin resistance and elevated plasma glucose as well as insulin levels before the onset of type 2 diabetes." (PMID 34367469, 2021). "Increased amounts of visceral adipose tissue is associated with adipose tissue insulin resistance and inflammation and results in a disturbed adipokine balance (low adiponectin and high leptin and tumor necrosis factor (TNF) concentrations)." (PMID 34925237, 2021). "In humans, the circulating concentration of TNF-α is strongly associated with impaired glucose tolerance, enhanced insulin resistance, and increased T2D risk." (PMID 34712684, 2021). "Since the discovery of its role in obesity-linked insulin resistance, TNF-α has been used to reproduce in vitro models of insulin resistance." (PMID 34361563, 2021). "Neuroinflammation has been linked with neuronal insulin resistance, due to the TNFα-JNK pathway-mediated IRS1 inhibition." (PMID 34069890, 2021). "Insulin resistance has also been associated with elevated levels of proinflammatory cytokines (Il-1, Il-6, TNF-α)." (PMID 34069618, 2021). "The levels of inflammatory markers, such as TNF-α and IL-6, which are the root causes of insulin resistance in type 2 diabetic patients with type 2 diabetes, were decreased in the CCL4 antibody injection group, compared with those in the IgG-treated DM group." (PMID 33968046, 2021). "Bloated fat cells secrete tumor necrosis factor alpha (TNF-α) and resistin, which are mediators of insulin resistance that are closely linked to type 2 diabetes." (PMID 32932138, 2020). "In visceral adipose tissue, the improved insulin resistance was associated with a decreased expression of pro-inflammatory markers such as IL-1β, TNF-α, and MCP-1 and with a decreased macrophage infiltration." (PMID 32326269, 2020). "Transfected cells were then analyzed for LPS-induced TNF-α production, which is a key proinflammatory cytokine implicated in the development of insulin resistance, by ELISA assay." (PMID 30941422, 2020). "Inflammatory cytokines such as TNFα and Il-6 also cause insulin resistance, and p38 MAPK itself is a crucial mediator of the expression of genes encoding for proinflammatory cytokines in skeletal muscles." (PMID 32899870, 2020). "The level of TNF-α has a strong positive correlation with HbA1c and was positively associated with insulin resistance." (PMID 32089876, 2020). "TNF‐α, an adipocytokine, which has been implicated in the development of insulin resistance, was considered to predict T2DM development as well." (PMID 32633001, 2020). "Pro-inflammatory M1-macrophages are key factors in generating inflammatory molecules, such as TNFα, IL-1ß and IL-6, that cause insulin resistance both in adipose tissue and other insulin-sensitive tissues." (PMID 32183037, 2020).